RANBP9 (RAN binding protein 9)
Diseases named in the same sentence as RANBP9 in open-access papers (continued):
Sharing a sentence is not in itself a finding about the gene and the disease.
cancer (16 papers, 2010 to 2025). A tumor composed of atypical neoplastic, often pleomorphic cells that invade other tissues. "Nevertheless, after it has become clear that RANBP9 is linked to critical cancer-causative pathways and to hallmarks of cancer in general, its investigative interest has shifted towards tumor-related paradigms." (PMID 34778565, 2020). "RanBP9 is a ubiquitously expressed protein that has been previously linked to exposure to genotoxic stress; however, its biological functions in normal and cancer cells are still unknown." (PMID 26943034, 2016). "In this regard, most of the knowledge about RanBP9 interactions and functions has been gained by using cancer cells where RanBP9 is generally expressed at levels higher than normal." (PMID 40223093, 2025). "RanBP9 and the CTLH complex have been implicated in a variety of physiological and pathological states including embryonic development and cancer." (PMID 40223093, 2025). "Moving on, we will then succinctly discuss RANBP9 in cancer generally, before focusing on the role of RANBP9 specifically in the cellular response to DNA damage of NCSLC cells." (PMID 34778565, 2020). "In cancer cells in vitro, generally it has been shown that downmodulation of RANBP9 results in decreased cell adhesion but more invasion ability, while overexpression has opposite effects." (PMID 31885576, 2019). "Given that RANBP9 is ubiquitously expressed, this eQTL in cancer cells cannot be explained by the activation of the gene and must reflect some change in gene regulation." (PMID 30205839, 2018). "In fact, RANBP9 is associated with pathways other than the DDR and consequently its absence might result in fatal damage to cancer cells." (PMID 34778565, 2020). "This warrants a pre-clinical investigation of RANBP9 as a potential target of therapy which may serve to ameliorate the cancer cell response and resistance to these drugs." (PMID 34778565, 2020). "ARMC8 is probably the second most investigated member of the CTLH complex in cancer after RANBP9." (PMID 31885576, 2019). "Mounting evidence have demonstrated that RANBP9 acted as an important mediator of DNA damage response (DDR), cell proliferation, migration, invasion, and apoptosis in human cancers." (PMID 34671019, 2021). "In summary, our study identifies RanBP9 as a new target of ATM, critically involved in the prompt activation of DDR signaling, repair of damaged DNA and cancer cell sensitivity to genotoxic stress." (PMID 26943034, 2016). "This phenomenon leads us to believe that it is always necessary in cancer cells and tissues to measure protein levels to evaluate the expression of RanBP9 rather than relying on the amount of RNA." (PMID 32346083, 2020). "Interestingly, RANBP9 has been shown to interact with oncogene c-MET, a key regulator in development and cancer stem cells." (PMID 30205839, 2018). "The RanBP9-TurnX mouse can be used for countless studies where it can be one “module” in compound models studying physiological functions and pathological roles that RanBP9 and the CTLH complex might have in metabolism, immune response, neurodegenerative diseases, and cancer." (PMID 40223093, 2025). "RANBP9 protein expression is high in advanced NSCLC, and patients expressing higher levels of RANBP9 protein have worse outcomes when treated with platinum-based regimens, which is in line with the hypothesis that RANBP9 is protective of cancer cells when subjected to DNA damage." (PMID 40883813, 2025).
tumor (15 papers, 2012 to 2025). "Despite the in vitro evidence showing that knockdown of RANBP9 results in increased tumor cell proliferation, invariably, tumors of different types display higher levels of expression compared to the normal counterpart." (PMID 31885576, 2019). "The Schild-Poulter lab has provided additional evidence for a pro-apoptotic tumor suppressive role of RANBP9." (PMID 29914204, 2018). "For example, RANBP9 has been shown to prevent the turnover of the mammalian homolog of the Lethal giant larvae (Mgl-1) tumor suppressor by facilitating the de-ubiquitination of the protein mediated by USP11." (PMID 29914204, 2018). "While it remains unclear whether RANBP9’s tumor suppressive effects is observed in vitro, most studies agree that RANBP9 is over-expressed in a variety of highly prevalent tumor types including that of NSCLC." (PMID 34778565, 2020). "RANBP9 has been shown to demonstrate tumor-suppressive effects in vitro." (PMID 34778565, 2020). "Thereby, RANBP9 has been proposed to function as a tumor suppressor itself." (PMID 31885576, 2019). "Finally, RANBP9 bound to TSSC3 (tumor-suppressing STF cDNA3) inhibited anchorage-independent growth and promoted anoikis in osteosarcoma cells." (PMID 31885576, 2019). "However, it is conceivable that RANBP9 opposes initiation but may later becomes advantageous for tumor progression, which is similar to TGF-β related signaling pathways." (PMID 34778565, 2020). "Due to the substantial number of ubiquitylation events that changes when their expression changes, RANBP9 and RANBP10 significantly impact NSCLC pathogenesis, including tumor cell proliferation and metabolism." (PMID 40883813, 2025). "However, this does not preclude the untested possibility that RANBP9 may possess a tumor suppressive function during the initial phases of NSCLC tumorigenesis due to its role in promoting genomic stability." (PMID 34778565, 2020).
RANBP9 also shares sentences with these, for which no sentence is quoted: neurodegenerative disease (2 papers); ovarian carcinoma (2); adenocarcinoma (1); amyotrophic lateral sclerosis (1); atherosclerosis (1); Cognitive impairment (1); endometrial cancer (1); gestational diabetes mellitus (1); hepatocellular carcinoma (1); hypopharyngeal squamous cell carcinoma (1); infection (1); influenza infection (1); neurological disorder (1); osteoarthritis (1); Parkinson’s (1); Pick disease (1); schizophrenia (1); squamous cell carcinoma (1).